FAP (fibroblast activation protein alpha)
Diseases named in the same sentence as FAP in open-access papers (continued):
Sharing a sentence is not in itself a finding about the gene and the disease.
tumor (continued). "A common tumor-associated antigen is the fibroblast-activating protein (FAP), which is detectable in tumor tissue of different malignancies." (PMID 36230765, 2022). "We next investigated the underlying mechanism by which the tumor cell–derived FGFBP1-triggered activation of the FGF2/FGFR1 axis induced FAPα expression in HSCs." (PMID 35951441, 2022). "FAP-expressing CAFs can promote tumor growth and invasion, and are often associated with poor prognosis." (PMID 35788730, 2022). "By stimulating the STAT3-CCL2 signaling pathway, the FAP induces immunosuppression by cancer-associated fibroblasts in the tumor microenvironment." (PMID 36065308, 2022). "Radionuclide-labeled fibroblast-activation-protein inhibitor (FAPI), as an important tracer for non-invasive imaging of the tumor microenvironment, can be used to evaluate the expression of FAP in cancer-associated fibroblasts, macrophages, and tumor cells." (PMID 34870727, 2022). "In the pooled analysis, high FAP expression was correlated with a greater risk of local tumor invasion, lymph node metastasis and distant metastasis, and with poor overall survival." (PMID 36428657, 2022). "Cancer-associated fibroblasts that express FAP show immunosuppressive proprieties for the tumor microenvironment." (PMID 35328635, 2022). "Fibroblast activation protein (FAP, FAP-α) is a type-II transmembrane serine protease overexpressed on the surface of cancer-associated fibroblasts (CAFs) in the tumor microenvironment (TME) in most epithelial malignancies." (PMID 36015106, 2022). "As known, the FAP-α was a membrane located protein, overexpressed on tumor associate fibroblast cell and pancreatic cell surface." (PMID 35058435, 2022). "Fibroblast-activation-protein (FAP) is overexpressed by cancer-associated fibroblasts (CAFs) in the tumor microenvironment." (PMID 35771317, 2022). "In conclusion, high expression of FAP in UVM tumor tissues was associated with poor patient prognosis." (PMID 35186170, 2022). "As part of the cellular components of the tumor microenvironment, there are cancer-associated fibroblasts with high expression of FAP while PSMA expression is associated with the continuous angiogenic processes in the extracellular matrix." (PMID 35456554, 2022). "Fibroblast activation protein (FAP), a type II transmembrane serine protease, is highly expressed in more than 90% of epithelial tumors and is closely associated with various tumor invasion, metastasis, and prognosis." (PMID 35692767, 2022). "Fibroblast activation protein (FAP), a type II transmembrane serine protease, is highly expressed in cancer-associated fibroblasts (CAFs) and critically associated with tumor growth, invasion, metastasis, immunosuppression and prognosis." (PMID 36276644, 2022). "Fibroblast activation protein (FAP) is heavily expressed in fibroblasts associated with the tumor microenvironment." (PMID 36500804, 2022). "TGFB1 encoded transforming growth factor-β (TGF-β) and FAP coded fibroblast activation protein alpha (FAP), both of which took part in disabling anti-tumor immune cells and impeding infiltration of immune cells." (PMID 35646049, 2022). "In solid tumors, the fibroblast activation protein (FAP), a member of the serine protease family, is expressed by tumor-associated fibroblasts at higher levels than on resident fibroblasts in healthy tissue." (PMID 34302116, 2022). "Tumor suppression is therefore presumed to be caused by radiation-induced DNA damage and subsequent apoptotic cell death of the FAP-expressing cells." (PMID 35608703, 2022). "In most epithelial cancers, FAP is selectively expressed on the cell surface of cancer-associated fibroblasts (CAFs) present in the tumor microenvironment." (PMID 35608703, 2022). "A fusion protein of IL-15-IL-15Ra and anti-FAP caused superior targeted anti-tumor killing ability, providing a rationale for the development of antibody-IL-15-IL-15Ra fusion proteins for cancer immunotherapy in the future." (PMID 36167591, 2022).
tumor (continued). "Recent studies have shown that ablation by FAP-expressing cells in a transgenic mouse model can lead to quick hypoxic necrosis and immunogenic tumor stromal cells of Lewis lung cancer, a process associated with the involvement of TNF-α and IFN-γ." (PMID 36046791, 2022). "Nevertheless, it is useful to identify treatments that selectively kill FAP+ locally activated fibroblasts, without causing systemic toxicity, which would permit treatments that aim to deplete tumor-associated FAP+ cells." (PMID 34490078, 2021). "The fibroblast activation protein (FAP) is a serine proteinase which is overexpressed on the cell surface of activated fibroblasts, particularly cancer-associated fibroblasts in tumor stroma." (PMID 34735669, 2021). "FAP is overexpressed by cancer-associated fibroblasts (CAFs) present in tumor microenvironment, which provides a high tumor uptake and a very low accumulation in normal tissues, resulting in excellent signal-to-noise ratios." (PMID 34680370, 2021). "Due to its cell surface localisation and selective overexpression in tumours, FAP is considered a potential diagnostic and therapeutic target and several approaches for its targeting were recently developed." (PMID 34282761, 2021). "Early studies that were conducted with dendritic cells transfected with mRNA that encodes FAP led to a reduction in tumor growth in various different tumor types." (PMID 34200702, 2021). "As an identifying surface marker of cancer-associated fibroblasts (CAFs) in other solid tumors, FAP also assists CAFs in suppressing antitumor immunity, promoting tumor growth and driving epithelial–mesenchymal transition (EMT)." (PMID 34068501, 2021). "Lymph nodes up to 7 mm in size showed only a weak FAP expression in less than 10% of the surrounding tumor-associated stromal cells (stain score 1+)." (PMID 33057927, 2021). "Another approach is tumor-associated fibroblasts which can be labeled via the fibroblast activation protein (FAP) with [68Ga]FAPI inhibitors." (PMID 34292419, 2021). "We and others have previously demonstrated that the expression of fibroblast activation protein (FAP), a characteristic marker of tumour-associated mesenchymal cells, is increased in GBM." (PMID 34282761, 2021). "Due to its overexpression in the tumor environment, combined with low expression in most normal tissues, FAP is considered as an important target for diagnostic imaging and anti-cancer therapies in nuclear medicine." (PMID 34417894, 2021). "Fibroblast activation protein (FAP) is expressed by the majority of pancreatic CAFs (90%) with a higher expression intensity on CAFs localized close to the tumor nests, and high FAP expression is associated with shorter overall survival." (PMID 34203869, 2021). "We observed that higher expression levels of αSMA and FAP in the tumor stroma were significantly associated with increasing depth of tumor invasion and lymph node metastasis, advanced pathological stage, and poorer prognosis in patients with ESCC." (PMID 33311557, 2021). "To detect tumor-associated protease activity, we introduce the FAP-responsive vasoprobe FAPVap, which undergoes a 34-fold increase in activity upon enzymatic cleavage." (PMID 34931988, 2021). "Similar to 4-1BB BsAbs, a FAP scFv-targeted GITRL fusion protein was developed to stimulate T cells exclusively in the presence of FAP-expressing tumor cells and cancer-associated fibroblasts." (PMID 34358141, 2021). "Increased FAP expression in GC has been associated with increased malignancy, poor prognosis, and tumor metastasis." (PMID 35155199, 2021). "Fibroblast activation protein (FAP) is a type II transmembrane glycoprotein expressed in dimer form on the surface of the tumor-associated cell matrix (CAFs)." (PMID 34671627, 2021). "Tumor-associated fibroblasts expressing FAP also show immunosuppressive potential against the TME, and the molecule itself is considered a new molecular target in cancer therapy." (PMID 33625532, 2021).
tumor (continued). "FAP+ PSC depletion increased tumor susceptibility to anti-CTLA-4 and anti-PD-1/anti-PD-L1 immunotherapies, the latter having a greater effect." (PMID 33499238, 2021). "Cancer-associated fibroblasts (CAFs) in the tumor stroma have an abundant and stable expression of FAP, which plays an important role in promoting tumor growth, invasion, metastasis, and immunosuppression." (PMID 34490078, 2021). "With the FAP-BiTE encoding virus, tumor-infiltrating PD-L1 positive T cells were induced to obstruct CAFs." (PMID 34681246, 2021). "We have previously demonstrated that tumour-associated CD90+CD73+ also express FAP at the mRNA level." (PMID 34740105, 2021). "Although our results are discrepant from previous works showing FAP expression was also elevated in early-stage CRC, we also found that FAP expression was associated with lymphatic invasion and tumor budding." (PMID 32733792, 2020). "In fact, in many biopsies, the vessel‐associated expression of FAP was more prominent than in the main tumor parenchyma." (PMID 33082953, 2020). "Cancer-associated fibroblasts (CAFs), including FAP, usually participate in extracellular matrix structure remodeling and tumor microarray reconstruction." (PMID 33109151, 2020). "In another example, RO6874813 is a 2:2 CrossMab that binds with high to fibroblast activation protein (FAP) on cancer-associated fibroblasts in tumor stroma and low affinity to death receptor 5 (DR5)." (PMID 32989604, 2020). "Most of the functions described for FAP are associated with its enzymatic activity involved in tissue remodeling, which helps tumor cells invade the surrounding tissue, penetrate the blood vessel wall, and travel to form distant metastasis." (PMID 32733792, 2020). "A high expression of FAP and low levels sFAP are significantly associated with high tumour diameter, high grade, and high pT stage, lymph node invasion, development of early metastases, and worse 5-year cancer specific survival of CCRCC patients." (PMID 33207686, 2020). "In the CD8-high group, FAP intensity was significantly associated with a higher total tumor density of FoxP3-positive immune cells and a higher ratio of epithelial-to-stromal density of CD8a T cells." (PMID 33153037, 2020). "A novel group of tracers that has emerged recently are substances targeting the fibroblast activation protein (FAP) on the surface of fibroblasts in the tumor stroma, so-called cancer-associated fibroblasts (CAFs) first published in 2018." (PMID 32942573, 2020). "In this sense, we demonstrated that FAP expression in CCRCC is associated to tumour aggressiveness and worse survival and suggested that this protein can be a good candidate as prognostic biomarker for this cancer." (PMID 33207686, 2020). "Fibroblast activation protein-α (FAP) is overexpressed in cancer-associated fibroblasts (CAFs), the primary constituent of tumor stroma." (PMID 32664210, 2020). "The gradual Bi-FAP/HER2-IL accumulation in the SK-BR3 and MCF-7 is based on both HER2 and FAP-directed binding of tumor cells and tumor associated fibroblasts." (PMID 33076292, 2020). "In tumors, overexpression of FAP by TAFs is associated with excessive tumor growth and formation of metastasis, which makes it an attractive target for diagnosis and therapy." (PMID 33076292, 2020). "Molecular biological analyses have shown that higher density of stroma with CAFs and FAP overexpression within the tumour is associated with increased tumour migration, invasion and therapy resistance." (PMID 32447444, 2020). "The over-expression of FAP has been associated with tumor incidence and microvessel density in various experimental mouse models." (PMID 32722460, 2020). "Preclinically, PT630 (GluBoroPro dipeptide), a pharmacological inhibitor of FAP, has been well demonstrated to cause a drastically reduced infiltration of myofibroblasts into tumor tissues, resulting in diminished tumor growth." (PMID 33158289, 2020).
tumor (continued). "Earlier studies on prognostic associations of FAP expression have detected good prognosis as well as poor prognosis associations of FAP expression in different tumor types, including CRC." (PMID 33153037, 2020). "FAP positive fibroblasts were linked to immunosuppressive functions within the tumor microenvironment." (PMID 31937798, 2020). "FAP has been shown to be overexpressed in tumor-associated stromal cells in epithelial tumors and its presence has been associated with worse prognosis." (PMID 32733792, 2020). "Treatment of biopsies of ascites or solid prostate cancer tissue samples with FAP-BiTE- expressing variant of EnAd was capable of activating tumor-infiltrating PD1+ T cells to kill CAFs." (PMID 33202717, 2020). "Fibroblast activation protein (FAP), a cell-surface serine protease, emerges as an imperative factor in cancer-associated fibroblasts (CAFs), especially relevant to tumor occurrence and progression." (PMID 33109151, 2020). "By using FAP-specific single chain variable fragment, this nano-approach efficiently eliminated CAFs and caused tumor suppression in tumor-bearing immunocompetent mice." (PMID 33292459, 2020). "FAP immunohistochemical expression was associated with high tumour diameter, tumour necrosis, sarcomatous phenotypes, high grade and high stage tumours, the development of early metastases, and worse survival of CCRCC patients." (PMID 33207686, 2020). "In conclusion, our work identified FAP/PDGFRβ dual positive tumor-associated pericytes as a distinct stromal cell type in the GBM tumor microenvironment." (PMID 33308315, 2020). "We demonstrate that an oncolytic adenovirus can target GBM-associated FAP+ stromal pericytes, in addition to killing tumor cells." (PMID 33308315, 2020). "Association of FAP expression with clinicopathological parameters demonstrated that FAP overexpression was associated with more advanced tumor stage (p = 0.02)." (PMID 32733792, 2020). "Fibroblast activation protein (FAP) is overexpressed in cancer-associated fibroblasts of several tumor entities." (PMID 30072500, 2019). "Strikingly, the authors observed significant loss of FAPα-positive cells from skeletal muscle in cachectic tumor models." (PMID 31058816, 2019). "Lo et al59 designed a CAR‐T therapy targeting fibroblast activation protein (FAP), which is a biomarker of tumor‐associated stromal cells, including CAF." (PMID 31339230, 2019). "Fibroblast activation protein (FAP) is predominately expressed on tumor associated fibroblasts but is also on a number of solid tumors." (PMID 30736355, 2019). "FAP loss was associated with improved antigen-specific tumor T cell infiltrate and enhanced collagen deposition." (PMID 30726287, 2019). "FAP is a post-proline peptidase selectively expressed during tissue remodeling and repair, such as with wound healing, and in the tumor microenvironment by cancer-associated fibroblasts." (PMID 30726287, 2019). "Recently published data suggests that FAP-mediated cleavage of collagen can be a substrate for binding of tumor associated macrophages scavenger receptor-A." (PMID 30726287, 2019). "Our results are consistent with this finding, in that FAP inhibition was associated with fewer tumor-infiltrating macrophages." (PMID 30726287, 2019). "The increased activity of the prolyl endopeptidase FAP enzyme is a hallmark of the tumor stroma, because of the accumulation and activation of cancer associated fibroblasts (CAFs)." (PMID 31881770, 2019). "FAPα-positive cells in the primary tumor microenvironment have been associated with immune suppression, promoting T cell exclusion via secretion of CXCL12." (PMID 31058816, 2019). "CAR T-cells targeting fibroblast activation protein alpha (FAP) which is expressed on the surface of cancer associated fibroblasts have shown efficacy in controlling tumor growth in preclinical models." (PMID 29872437, 2018).
tumor (continued). "On the other hand, immunosuppression by FAP+ tumour associated macrophages is mediated by heme-oxygenase-1 (HO-1)." (PMID 28158223, 2017). "The fibroblast activation protein α (FAPα) is known to be associated with immunosuppression in the tumor." (PMID 28881756, 2017). "The current study is to develop a gentle and efficient method for purification of fibroblast-activation protein positive (FAP+) cancer-associated fibroblasts (CAFs) from tumor tissues." (PMID 28890895, 2017). "High FAP expression is associated with tumor re-growth, recurrence, and poor clinical outcome in pancreatic cancer." (PMID 28881756, 2017). "All of these results suggest that FAP α is an adaptive tumor-associated antigen useful for tumor immunotherapy." (PMID 26985769, 2016). "Accordingly, targeting FAP by active immunotherapy or T cells engineered to express a FAP-specific CAR decreases tumor growth and this is linked to reduced angiogenesis, changes in extracellular matrix proteins and augmented antitumor immunity." (PMID 26943036, 2016). "The overexpression of FAP in CAFs and in tumor cells has been associated with higher risk of metastases and worse survival in several solid tumors." (PMID 28033421, 2016). "Genetic deletion or pharmacological inhibition of FAP can inhibit tumour growth in mouse models, suggesting that FAP is implicated in tumorigenesis, and it has since become a target for oncology treatment." (PMID 26635356, 2016). "Specifically targeting tumour-associated fibroblasts, utilising their expression of fibroblast activation protein α (FAP), remains at the preclinical stage of development." (PMID 26784251, 2016). "FAP is an activated fibroblast-specific protease that is implicated in modifications of tumor stroma and correlated with higher histological grades of malignancies, metastasis, and poor patient prognosis." (PMID 26934296, 2016). "Elimination of FAP-positive fibroblasts also reduced the recruitment of tumor-associated macrophages or myeloid-derived suppressor cells (which produce Th2 cytokines and increase recruitment of dendritic cells and CD8+ T cells)." (PMID 26828520, 2016). "FAP regulates proteolysis of the extracellular cell matrix in tumor stroma, causing stromal cell proliferation and invasiveness." (PMID 27881889, 2016). "A statistically significant association was found between FAP expression and pathological parameters of tumor aggressiveness." (PMID 28033421, 2016). "In vivo studies have demonstrated that increased FAP α expression is associated with increased tumor growth rate and promotes neovascularization." (PMID 26985769, 2016). "Genetic depletion of FAP, vaccines targeting FAP or T cells with a FAP-specific chimeric antigen receptor (CAR) inhibit tumor growth in part by enhancing tumor-specific immune responses; however the underlying mechanisms remain poorly understood." (PMID 26943036, 2016). "S100A4 is a marker of fibroblasts in tissues undergoing remodelling, for example in fibrosis in the renal interstitium, while FAP expression is associated with activated fibroblasts in tumour stroma and fibrotic disease." (PMID 25978616, 2015). "The patients with FAP overexpression (particularly expression in tumor cells) tended to have a higher risk of distant metastases; however, this risk was not significantly different from those of the other groups." (PMID 25775399, 2015). "Nevertheless, in group B, the statistical outcomes revealed that patients with FAP overexpression in tumor cells had a greater risk of local tumor invasion than those patients with FAP overexpression in stroma cells in group A (OR: 6.56)." (PMID 25775399, 2015). "Further subgroup analysis based on the FAP expression status in different cells revealed that the patients with FAP overexpression in tumor cells had a higher risk of poor overall survival and greater odds ratios of lymph node metastases." (PMID 25775399, 2015).